IDH1 (isocitrate dehydrogenase (NADP(+)) 1)
Diseases named in the same sentence as IDH1 in open-access papers (continued):
Sharing a sentence is not in itself a finding about the gene and the disease.
glioma (continued). "Interestingly, there is a clear mutation selection bias in gliomas (IDH1 R132H) versus chondrosarcomas (IDH1 R132C), and to date, IDH1 R132Q has only been reported in chondrosarcomas." (PMID 40188944, 2025). "Since then, the field of genomics has opened the door to understanding the genetic disposition to many neurologic diseases, including studying IDH mutations in gliomas and IDH1 mutations in glioblastomas, as well as understanding SCN1A mutations associated with epilepsy." (PMID 40806492, 2025). "Additionally, glioma stem-like cells with IDH1 mutations secrete granulocyte colony-stimulating factor (G-CSF), reprogramming tumor-infiltrating neutrophils into non-suppressive states, which further alters immune dynamics." (PMID 40931345, 2025). "According to the 2021 WHO classification of central nervous system tumors, IDH1 mutations are indicative of lower-grade gliomas, which might explain why samples with higher HRD Index are associated with poorer prognosis." (PMID 41417782, 2025). "Nevertheless, other factors may play a role, as IDH1-wildtype GBM demonstrates a more significant association with MGMT status than IDH1-mutated gliomas." (PMID 40565099, 2025). "Mutations in Isocitrate Dehydrogenase 1 (IDH1) are found in over 80% of WHO grade II/III gliomas." (PMID 41426059, 2025). "The IDH1/2 mutation plays a crucial role in glioma in glioma diagnosis, treatment, and prognosis." (PMID 40134593, 2025). "The strong alignment of our findings with these studies suggests that gray-level texture analysis could serve as an imaging surrogate for IDH1 mutation detection, potentially aiding in noninvasive glioma classification." (PMID 40299088, 2025). "IDH1 mutant gliomas are more predisposed to benefit from gross total resection (GTR)." (PMID 40944023, 2025). "IDH1-mutant glioma is associated with the proneural subtype and a better prognosis." (PMID 40564017, 2025). "Interestingly, HDAC inhibitors have shown heightened efficacy in gliomas harboring the IDH1 R132H mutation." (PMID 40565099, 2025). "Additionally, combining 5hmC biomarkers with IDH1 mutation status enhanced differentiation between glioblastomas (GBM) from WHO II-III gliomas." (PMID 40055844, 2025). "Based on the known associations between younger age and IDH1/2-mutant gliomas, we assessed whether age independently modulates anatomic–molecular correlations." (PMID 41377022, 2025). "In this large-scale Chinese cohort, we first confirmed a strong link between tumor location and molecular subtype: Frontal gliomas had IDH1/2 mutations in 63.5% of cases, while temporal (80.3%) and thalamic/basal ganglia gliomas (90.4%) were predominantly IDH1/2-wild-type." (PMID 41377022, 2025). "Since the initial discovery of IDH1 driver mutations in glioma by Professor Parsons DW in 2008, the role and clinical significance of these mutations have gradually become a major focus in glioma research." (PMID 40661781, 2025). "Gliomas harboring mutated IDH1/2 show a better prognosis than IDH1 wild-type (wt) tumors of the same grade, which might result from the inhibition of DNA repair functions." (PMID 40564198, 2025). "The data strongly indicate that ALKBH2-mediated DNA repair is involved in the defense against ART-induced DNA damage and propose ART as a therapeutic supplemental agent notably for IDH1/2-mutated gliomas and presumably also other cancers displaying this mutation." (PMID 40564198, 2025). "Developing binders selective to mut-IDH1 over wt-IDH1 could have wide-ranging applications, from PET radiotracers for early, non-invasive diagnosis of IDH1-associated glioma to anti-brain cancer drugs." (PMID 40569935, 2025). "In syngeneic mouse models, IDH1 mutations in gliomas downregulate genes related to chemotaxis, thereby reducing immune infiltration, including that of microglia and neutrophils, which may enhance patient survival." (PMID 40076738, 2025).
glioma (continued). "It served, first, as a tool for exclusionary diagnosis, by ruling out molecular hallmarks of other histologically similar malignancies—such as IDH1/2 mutations in high-grade gliomas and H3F3A mutations in certain embryonal tumors—thereby consolidating the diagnosis of AT/RT." (PMID 41383551, 2025). "IDH1/2 mutations are druggable targets and are already exploited for therapeutic purposes in gliomas, cholangiocarcinoma, and acute myeloid leukemia (AML), but, as we will see later, their significance as targets in CS clinical management is still under evaluation." (PMID 40004005, 2025). "Additionally, glioma cells harboring IDH1 mutations demonstrate increased sensitivity to glutaminase inhibition, suggesting that glutaminolysis serves as a compensatory mechanism essential for maintaining metabolic homeostasis." (PMID 40942013, 2025). "The immune landscape of gliomas is modulated by IDH1/2 genetic alterations, notably, PD-L1 expression is substantially decreased in mutated tumors, providing a mechanistic basis for immune checkpoint inhibitors (ICIs) in IDH1/2 wild-type (wt) patients." (PMID 40927709, 2025). "Forest plot data for glioma IDH1 mutation status classification." (PMID 40127071, 2025). "IDH1 mutant gliomas with mutations in TERT promoter have exhibited better prognosis." (PMID 40337276, 2025). "Intracranial glioma models with the IDH1-R132H mutation have also been developed." (PMID 40647477, 2025). "Additionally, it has been reported that gliomas with IDH-1/-2 mutations are more likely to cause epileptic seizures than IDH-1/-2-wild-type tumors." (PMID 39917141, 2025). "However, mutations in isocitrate dehydrogenase 1 and 2 (IDH1/2) are observed in approximately 80% of gliomas." (PMID 41369374, 2025). "In tumors, notably in gliomas, IDH1 and IDH2 are frequently mutated." (PMID 40564198, 2025). "Furthermore, oral microbiota differences are associated with both glioma grade and IDH1 mutation status." (PMID 41516317, 2025). "Interestingly, malignant progression of mutant IDH1-driven lower grade gliomas is associated with partial DNA demethylation via an inability of rapidly proliferating cells to maintain methylation." (PMID 40188944, 2025). "IDH1 mutations occur in gliomas more frequently than IDH2 mutations." (PMID 40428422, 2025). "Our study suggests that the prediction accuracy of glioma IDH1 mutation status reaches 95.63%." (PMID 40323991, 2025). "Moreover, most molecules were associated with the end-stage glioma, mesenchymal glioblastoma with wild-type IDH1." (PMID 40895574, 2025). "Furthermore, IDH1 variants can interfere with cholesterol metabolism in astrocytes, and impact the brainstem and cerebellum, manifesting as gliomas in the posterior fossa." (PMID 39634128, 2025). "Additionally, this study found that the abundance of Bacillota was significantly lower in patients with IDH-1 mutated gliomas compared to IDH wild type." (PMID 40227812, 2025). "We also examined whether genes upregulated after KAT5 loss (Neural G0 genes) differ significantly in expression in clinical glioma tumor surgical samples by IDH1/2 mutation status and/or grade." (PMID 40346033, 2025). "Furthermore, gliomas with IDH1 mutations exhibit lower ITSS grades than their IDH wild-type counterparts." (PMID 40052095, 2025). "Moreover, oral human microbiota composition differs significantly by glioma grade and IDH1 mutation status." (PMID 41516317, 2025). "Therefore, histopathological confirmation of markers like IDH1 mutation not only reinforces predictive model reliability, bolsters diagnostic decision-making, and contributes to glioma treatment management." (PMID 40299088, 2025). "In retrospect, including any tumor harboring IDH1 mutation may have hindered the study, especially due to the inclusion of gliomas (47% of the study population) where ivosidenib has minimal activity in enhancing disease." (PMID 41138165, 2025).
glioma (continued). "However, their limitations include high equipment costs, difficulty distinguishing D‐2HG from its chiral enantiomer, and inability to spatially and quantitatively access the IDH1 mutational heterogenicity in glioma samples." (PMID 40171868, 2025). "In addition, the IDH1 R132H mutation independently predicted a long RFP in patients with low grade remedial glioma (HR 1.073, 95% CI 0.151–0.775, p <.01)." (PMID 40014162, 2025). "IDH1 mutations are commonly found in low-grade gliomas, but are rare in glioblastomas (GBM)." (PMID 40881678, 2025). "On the contrary, lower levels of MEX3A were observed in IDH1 mutated gliomas." (PMID 40958871, 2025). "Interestingly, while ATRX loss is associated with increased immune activation in glioma, co-occurring IDH1 mutations can mask this effect, a suppression reversible with mutant IDH1 inhibition." (PMID 40931345, 2025). "Therefore, the IDH1 R132H gene mutation was a specific mutation in glioma and was a driver of glioma development." (PMID 41381536, 2025). "FRIL, which is overexpressed in high grade glioma, mainly associated with IDH1/2 wildtype and unfavorable prognosis of these glioma patients, has also been indicated as a biomarker together with ferritin heavy chain to predict prognosis and temozolomide resistance in glioma patients." (PMID 38607010, 2024). "Additionally, our data shed light on the association between IDH-1 wildtype status and high-grade gliomas." (PMID 39348350, 2024). "The radiomics model established by DWI, DCE and APTW images could be used to detect IDH-1 mutation and Ki-67 expression in glioma patients before surgery." (PMID 39285364, 2024). "IDH1 mutation and 1p19q-Codel correlate with a good prognosis in glioma." (PMID 39502752, 2024). "REST knockdown differently affected cell invasion of the parental or IDH1-mutated glioma cells." (PMID 38711090, 2024). "Moreover, the α-KG-related metabolic reprogramming and hypermethylation phenotype are intimately associated with the differentiation of IDH1-mutant gliomas." (PMID 39872214, 2024). "In gliomas, R132H is the most common IDH1 mutation, and R172K is the most common IDH2 mutation." (PMID 38951603, 2024). "Other biomarkers of considerable relevance in the early diagnosis of GBM are the mutated mRNA encoding the isocitrate dehydrogenase 1 (IDH1) enzyme and a group of miRNAs, among which are miR-21, which are present in glioma-derived EVs and involved in the vascular proliferation of glioma." (PMID 39194524, 2024). "A significant proportion of gliomas carry mutations in the IDH1 and IDH2 genes." (PMID 38540734, 2024). "Two additional studies suggest that DUSP-4 may be a diagnostic and prognostic marker for IDH1 mutant gliomas, GNA12 signaling regulation promotes transcriptional and phenotypic responses to GBM tumor invasion." (PMID 39830513, 2024). "They conducted extensive analysis regarding the interpretability of their model and reported that the presence of necrosis and IDH1 mutation status were the most attributed features in gliomas from the TCGA-LGG dataset, which is in line with the current WHO classification." (PMID 40603567, 2024).
glioma (continued). "Additionally, 1H-MRS has unique sensitivity to 2-hydroxyglutarate (2-HG), a metabolite elevated exclusively in tumor cells with the oncogenic isocitrate dehydrogenase (IDH1) mutation, frequently found in gliomas and secondary glioblastomas." (PMID 39728759, 2024). "Finally, by integrating data from the CGGA and TCGA databases, it was validated that ITGB4 expression was lower in IDH1-mutant gliomas, and patients with lower ITGB4 expression were associated with better prognosis." (PMID 38982076, 2024). "The decrease in homocysteine in IDH1-mutated glioma patients might be due to a shift toward glutathione synthesis in the hypoxic tumor environment to counterbalance reactive oxygen species." (PMID 39227460, 2024). "The ANT relationship of IDH1 and RB1 mutations in brain tumors may have arisen due to the mutation preference of low- and high-grade gliomas that are respectively enriched with IDH1 mutations and mutations in Rb pathways including RB1 mutations." (PMID 39160568, 2024). "Consistently, IF staining results showed that the IDH1 mutation significantly decreased 5-hmC levels in OGDH-silenced glioma cells, and immunoblotting data showed that the IDH1 mutation significantly elevated H3K27me3 and H3K4me3 levels in the OGDH-silenced U87 cells." (PMID 39872214, 2024). "We hypothesize that D-2HG produced by IDH1 mutation may have anti-cancer properties in gliomas, leading to better prognosis in IDH1-mutant cases." (PMID 38982076, 2024). "Performance is worse for smaller subgroups (e.g., 1p/19q codeleted or IDH1/2 mutated gliomas)." (PMID 38791871, 2024). "Our study confirms that liquid biopsy and cfDNA could be a complementary methods to tissue biopsy in the detection of IDH1 mutation, which can be used as a strong prognostic and predictive biomarker for a favorable clinical outcome in patients with glioma." (PMID 38172718, 2024). "IDH1 mutations were associated with a favorable prognosis than diffuse IDH1 wild-type gliomas." (PMID 39192927, 2024). "Tumors arise from gene mutations, and IDH1 mutations are glioma-specific, and the mutations are capable of causing HIF-1α overexpression, which may be important for the development of gliomas." (PMID 38734702, 2024). "Within the last decade, the WHO grading system of gliomas that is historically based upon histopathologic markers of malignancy has been significantly altered and augmented by use of molecular alterations like isocitrate dehydrogenase (IDH)-1/2-mutation." (PMID 39593128, 2024). "The mutation most frequently found in gliomas is that affecting the IDH1 gene." (PMID 39763601, 2024). "We and others have previously reported a reproducible extracellular metabolome across a diverse array of gliomas, including elevated D-2-hydroxyglutarate (D-2-HG) within gliomas harboring a mutation in isocitrate dehydrogenase 1 (IDH1), the most common glioma subtype in most young adult patients." (PMID 39123433, 2024). "In addition, a subset of IDH1mut gliomas that recur and subsequently demonstrate rapid growth phenotypes have been shown to produce far lower levels of D-2-HG even while retaining IDH1 mutations." (PMID 38445960, 2024). "The IDH1-mutant tumors recapitulated the proneural glioma while retaining the mutation." (PMID 38334611, 2024). "Recognition of the importance of IDH1/2 mutations in progression of diffuse gliomas advanced our understanding of glioma biology, however the full impact of a state of DNA and histone hypermethylation on gene regulatory networks and cell functions is less clear." (PMID 38711090, 2024). "Gliomas with IDH1 mutation show a different metabolic pattern compared to other solid tumors." (PMID 39457600, 2024). "Additionally, we observed that a mutant IDH1 inhibitor significantly raised α-KG levels and aided the differentiation of IDH1-mutated glioma cells with low OGDH expression." (PMID 39872214, 2024).
glioma (continued). "Notably, IDH1/2 mutations, frequently seen in adult gliomas, are rare occurrences in PLGGs and cluster among adolescent patients." (PMID 39056798, 2024). "However, when compared to IDH1 wild-type gliomas, IDH1 mutations and high levels of D-2HG are markers of better prognosis and are associated with anti-tumor growth effects." (PMID 38982076, 2024). "While early mutations in chromatin modifiers like IDH1/2 are pivotal in glioma development, their roles may evolve from driving to secondary as the cancer progresses, challenging the effectiveness of targeting these mutations." (PMID 39199633, 2024). "IDH1 mutations in gliomas almost exclusively occur at a specific arginine residue (Arg132)." (PMID 39605316, 2024). "For example, age is a risk factor for the development of high-grade glioma; young patients are more likely to suffer from IDH1-mutant glioma, and their postoperative survival and clinical prognosis may be more optimistic." (PMID 39139289, 2024). "An experimental study indicated that IDH1 mutation and D-2HG could induce oxidative stress, autophagy, and apoptosis in glioma cells." (PMID 38982076, 2024). "However, some papers demonstrate inhibited motility of glioma cells with the IDH1 R132H mutation compared to IDH1 wild-type cells." (PMID 39596246, 2024). "Using advanced iPSC glioma models driven by glioma driver mutations, we show that this AS signature could be enhanced by EGFRvIII and inhibited by in situ IDH1 mutation." (PMID 38662454, 2024). "Therefore, preoperative evaluation of Ki-67 expression and IDH-1 mutation in glioma is of great significance for formulating treatment plans and evaluating prognosis." (PMID 39285364, 2024). "However, low-grade gliomas with isocitrate dehydrogenase 1 gene (IDH1) and IDH2 mutations, which transform to malignancy are rarer in pediatrics." (PMID 38368566, 2024). "In the vast majority of IDH mutated gliomas (>90%), these mutations are located at codon 132 of IDH1 and result in an arginine-to-histidine (R132H) substitution at the active site, although other mutations affecting the corresponding arginine residue in IDH1 or IDH2 have been described as well." (PMID 39203017, 2024). "IDH1 variants also improve the overall prognosis of glioma patients, which may be useful for the early diagnosis of related seizures." (PMID 38641945, 2024). "Seven types of IDH1 mutations have been identified in gliomas." (PMID 39192927, 2024). "We next aimed to correct the IDH1 mutation in biologically more complex glioma models." (PMID 39605316, 2024). "In addition, the ANT presentation of PTEN and IDH1 mutations have been previously recognized for some tumor types such as gliomas." (PMID 39160568, 2024). "The IDH1 mutation inhibits the virus-induced IFN antiviral response in glioma cells." (PMID 38577683, 2024). "Similarly, glioma patients with high-TBC1D1 tumors exhibited a higher frequency of mutations in IDH1." (PMID 38529286, 2024). "Our study provides crucial insights into the frequency of IDH1 mutations in gliomas in Kenya." (PMID 38444421, 2024). "Considering this may be an early clonal mutation, different IDH1 mutations may indicate the simultaneous progression of two separate low-grade gliomas." (PMID 38919539, 2024). "This provides an incentive to develop novel, biologically relevant IDH1-mutant tumor models to further elucidate the significance of the IDH1R132H mutation in glioma biology and assess the therapeutic potential to correct a potentially causative mutation in brain tumors." (PMID 39605316, 2024). "Five of 11 low-grade gliomas had the IDH1 p.R132H mutation in tissue and plasma." (PMID 38172718, 2024).